MSLN (mesothelin)
Diseases named in the same sentence as MSLN in open-access papers (continued):
Sharing a sentence is not in itself a finding about the gene and the disease.
tumor (continued). "Compared to conventional CAR-T cells, CAR-ss-T cells produced higher levels of interferon-γ (IFN-γ), IL-2, tumor necrosis factor-α (TNF-α) and granzyme B (GZM) against MSLN-expressing HGC27 and MKN45 tumor cells." (PMID 38368374, 2024). "Various tumor markers were identified, including calretinin (CALB2), mesothelin (MSLN), type III collagen (COL3A1), and secretory leukocyte peptidase inhibitor (SLP1)." (PMID 39376629, 2024). "Compared with anti-MSLN CAR-T cells, anti-MSLN CAR-T cells expressing RIAD (CAR-RIAD-T cells) showed enhanced TCR signaling, increased cytokine release, and enhanced killing of tumor cells after exposure to PGE2 or adenosine in vitro." (PMID 39023820, 2024). "Compared with conventional CAR-T cells, anti-MSLN CAR-T cells coexpressing IL-7 and CCL19 exhibited greater expansion and migration ability in vitro and demonstrated greater inhibition of tumor growth in PC and human mesothelioma mouse models." (PMID 39023820, 2024). "Selective expression of MSLN, MUC4, ANXA10, and GPC-1 in the neoplastic tissue compared to non-tumor ductal and acinar tissues (p < 0.001)." (PMID 39062863, 2024). "Mechanistically, MSLN facilitated the expression and activation of MET through the c-Jun N-terminal kinase (JNK) signaling pathway, which allowed tumor cells to disrupt tight junctions and the integrity of the BBB and thereby penetrate the barrier." (PMID 38570866, 2024). "MSLN-CAR-NK92 cells, for example, specifically target MSLN-positive cancer cells in vitro, demonstrating enhanced anti-tumor effects and increased NK cell infiltration in vivo." (PMID 39397869, 2024). "Significant anti-tumor effects were observed, where 7 × 19 mesothelin-targeting CAR-T proved more efficacious than CAR-T only targeting mesothelin." (PMID 38339310, 2024). "It was found that mesothelin is highly expressed in ovarian cancer, and MSLN CAR-T cells can target and kill tumor cells with strong anti-tumor activity, and clinical reports showed that it has safety and efficacy." (PMID 39253578, 2024). "Thus, targeting MSLN may be an effective strategy to inhibit tumor progression." (PMID 38628720, 2024). "CCR2b-anti MSLN CAR-T cells exhibited enhanced migration and infiltration into tumor tissue, displaying superior anti-tumor efficacy, particularly in non-small-cell lung carcinoma." (PMID 39134804, 2024). "We have shown, for the first time, the potential of an anti-MSLN nanobody for PET/CT imaging and demonstrated the selective accumulation of [68Ga]Ga-NODAGA-S1 in MSLN+ tumour, with high contrast images, shortly after systemic injection." (PMID 37388728, 2023). "Moreover, animal models with orthotopic expression of human antigens, such as exemplified by mice expressing the human mesothelin protein in the lung, could be exploited to assess the in vivo antigen sensitivity of CAR T cells and the risk for on-target off-tumor toxicity." (PMID 37287982, 2023). "As shown in the literature, MSLN and CXCR4 are potential agents for targeted anti-tumour or endo-radioligand therapy." (PMID 37047331, 2023). "Data also indicate that advanced tumor stages (III and IV) and high-grade EOC patients express higher levels of mesothelin in their tumors." (PMID 37244991, 2023). "In detail, the OC tumor tissue and PSO showed MSLN expression on some cells, as well as positive expression of MUC1 and CD276." (PMID 38162496, 2023). "At the single-cell level, tumor cells expressed low levels of CHST11 compared with ALDH3B1, EGFR, ERAP2, MSLN, and NCEH1." (PMID 37251940, 2023). "To examine the function of ROS in tumor killing ability of ACOD1-/- MSLN-CAR-iMACs, we added the anti-oxidant reagent N-Acetyl-L-cysteine (NAC) to eliminate ROS in the tumor-iMAC co-culture system." (PMID 37723178, 2023). "The anti-MSLN ∼ 80 kDa VH-FcsPET-agents demonstrated improved accumulation within theMSLN-positive HCT116 tumor compared to the 150 kDa IgG1 PET-agent,[89Zr]Zr-m912." (PMID 38027361, 2023).
tumor (continued). "Three genes with gains (TORC1, MSLN, and STUB1) were selected as potential markers of the progression of a CRC tumor from HGIL to ISL." (PMID 35920319, 2023). "Of note, similarly to MSLN, MUC4 was recently considered as a valuable tumor-related target for immunotherapy and a potential candidate vaccine for PDAC, thanks to its selective expression on PDAC cells." (PMID 37760554, 2023). "Mesothelin-targeting CAR T cells and NK cells show robust anti-tumor efficacy against cancers in human xenograft models, such as TNBC, pancreatic, malignant pleural mesothelioma, ovarian, and GC." (PMID 38067366, 2023). "MSLN+ tumor cells were detected by FACS in most spleens and in mice treated with M1xx CAR T cells showed a higher CAR T cells:MSLN+ tumor cells ratio than M28z CAR T cell-treated mice." (PMID 36746513, 2023). "MesobsFab, a Fab-like format, targeting mesothelin and CD16, which facilitates the recruitment and infiltration of NK cells into tumor spheres, leading to strong, dose-dependent cell-mediated cytotoxicity in mesothelin-positive TNBC." (PMID 37660039, 2023). "Listeria-based vaccines have been used to express mesothelin, which is highly expressed in PDAC tumours." (PMID 37686543, 2023). "Several clinical trials are also currently underway to evaluate the anti-tumor efficacy of CAR T-cells producing antibodies against CTLA-4 and PD-1 in MUC1+, EGFR+, and mesothelin+ solid tumors (NCT03179007, NCT03182816, and NCT03182803)." (PMID 37020537, 2023). "To determine in vivo anti-tumor efficacy we tested the EGFR (n=4), HER2 (n=4), and mesothelin (n=3) T-BsAbs in an intraperitoneal model of DSRCT (JN-DSRCT-1-luc), which more closely recapitulates human disease than a standard flank xenograft." (PMID 37091153, 2023). "Expanding on the MSLN-mediated tumor-suppressive role of PSCA, the introduction of PSCA to these PDAC cell lines led to a reduction in the levels of MSLN." (PMID 37894284, 2023). "Briefly, mesothelin+ 4662 PDAC cells were transduced with mCerulean3 29 and were subcutaneously inoculated into syngeneic mice and tumor-bearing mice were treated." (PMID 37607999, 2023). "Regarding adoptive cell treatment, tumor-directed anti-mesothelin CAR-T cells and M2 inhibitors have been shown to have anti-tumor efficacy." (PMID 37525217, 2023). "Concordance was high between PDX models and paired tumor samples for expression of key markers of interest (BAP1, WT1, mesothelin, PD-L1 and VISTA) and genomic alterations." (PMID 36380343, 2022). "Some targetable antigens are mucin-1 (MUC1), mesothelin (MSLN), and CEA, while CART cells against the tumor-specific antigen (TSA) are currently under study." (PMID 35743107, 2022). "MSLN-CAR NK cells constructed based on NK-92 cells can effectively kill MSLN-positive GC cells in vitro and inhibit tumor growth in the PDX model, with a large number of NK cells infiltrating the tumor." (PMID 36341377, 2022). "Phase I clinical trials have shown that MSLN-targeted CAR T-cell therapy is safe, but its efficacy is very limited due to insufficient tumor infiltration and the persistence of CAR T-cells." (PMID 36497465, 2022). "Limited nonclinical cellular kinetics data reported in the literature have shown that i.v. administration of anti-mesothelin and anti-BCMA CAR T cells in tumor bearing NSG mice would lead to a Tmax ranging from 5 to 14 days." (PMID 35869348, 2022). "The fusion of anti-mesothelin Fv (SS1) with PE38 [SS1(dsFv)PE38] has been efficiently used to target mesothelin, a 40-kD tumor differentiation antigen." (PMID 35744957, 2022). "In this study, coadministration of GO restored GD2, MSLN and EGFRvIII CAR-T cell proliferation, leading to increased tumor cell death." (PMID 35211124, 2022). "Firstly, more solid tumors with high expression of MSLN and PDL1 are needed to determine the overall anti-tumor effect of this novel vaccine in the future." (PMID 35795680, 2022).
tumor (continued). "So far, panels of binders have been isolated against different viral and tumor targets, including the SARS-CoV-2 RBD, HIV-1 ENV protein, mesothelin and FLT3." (PMID 35464476, 2022). "The expression of three hub genes, COL7A1, MSLN, and CHRDL1, was significantly correlated with tumor-infiltrating monocytes." (PMID 35993054, 2022). "Tumor distribution of a theoretical trastuzumab-based RIT was simulated at a dose of 140 μg/kg, which is the maximum tolerated dose for an anti-mesothelin RIT that is currently being evaluated in clinical trials." (PMID 35250584, 2022). "Two mesothelin-targeted ADC drugs including Anetumab ravtansine and DMOT4039A have presented active anti-tumor effects in the preclinical studies and further clinical trials are in progress." (PMID 35795565, 2022). "It is possible that 22A31 interrupts the heterotypic interaction between ERC/mesothelin and other molecules such as CA125/MUC16 on the surface of tumor cells or adjacent stromal cells, leading to the suppression of proliferative activities of carcinoma cells." (PMID 35565327, 2022). "We found remarkable concordance in the protein expression of several key markers (BAP1, WT1, mesothelin, PD-L1, and VISTA) between the primary tumor and PDX tumors." (PMID 36380343, 2022). "MORAb-009 has a high affinity for mesothelin, and a preclinical evaluation demonstrated that it could inhibit the adhesion between cell lines expressing mesothelin and MUC16 (CA125), as well as causing cell-mediated cytotoxicity in mesothelin-bearing tumour cells." (PMID 35565412, 2022). "We also highlight the progress made in anti-MSLN CAR T cell engineering which resulted in increased infiltration, persistence and anti-tumor activity." (PMID 33588928, 2021). "Using an ectopic xenograft model with high expression of FOLR1 and MSLN, complete tumor eradication was achieved in one of five treated mice in the Tandem-CAR group, with tumor outgrowth observed in the single-target CAR-T groups." (PMID 34803504, 2021). "Similar results in terms of antitumor activity were observed in a different model system using a CAR specific for mouse mesothelin protein, which is endogenously expressed by ID8 tumor cells." (PMID 33563975, 2021). "The results showed that the tumors of mice injected with anti-MSLN were smaller than those injected with PBS or CA125, indicating that tumor growth was inhibited by anti-MSLN." (PMID 33613114, 2021). "First, we assessed the MSLN-specific tumor lysis capability of P4 CAR-T cells using the CRL5826 cell line, which is both MSLN-positive and PD-L1-positive." (PMID 34381179, 2021). "Like NK-92, stable expression of mesothelin-CAR was achieved in iPSCs, and subsequent functional assays indicated enhanced tumor specificity and killing in iPSC-derived CAR-NK cells." (PMID 34134774, 2021). "To further determine if the potent anti-tumor activity of T cells bearing a KIRS2/Dap12-CAR is dependent on the CD19 specificity, we generated an additional CAR targeting mesothelin (SS1 KIRS2/Dap12-BB)." (PMID 34703879, 2021). "The corresponding genes of these three DMPs were mesothelin (MSLN), protein kinase cAMP-dependent type II regulatory subunit beta (PRKAR2B), and msh homeobox 1 (MSX1), all of which correlated with tumor development, malignancy, and treatment." (PMID 33995018, 2021). "Retargeted Herpesviruses allow selective infection of cancer cells trough an antibody fragment targeting a given tumor antigen (e.g., HER2, MSLN, PSMA)." (PMID 34948316, 2021). "For example, EOC has a large number of potential tumor biomarkers, including CA-125, WFDC2 (HE4) protein, and serum mesothelin." (PMID 33816311, 2021). "Overexpression of mesothelin alone is sufficient to constitutively activate the NFκB, MAPK, and PI3K intracellular pathways promoting tumor cell proliferation and resistance to apoptosis." (PMID 33442419, 2021).
tumor (continued). "According to these findings, mesothelin and CD19 CAR T cells were administered to three patients in order to target tumor cells and to deplete B cells." (PMID 34943898, 2021). "Our study provides additional support for considering MSLN targeted therapies in HGSC, since, as we show here, it is a strong element that promotes tumor aggressiveness and more than 70% of HGSC and peritoneal metastasis displayed MSLN overexpression." (PMID 32612258, 2020). "It is known that the mesothelin gene encodes a precursor protein that is cleaved into membrane-bound mesothelin and soluble MPF, whose serum level reflects the expression of target antigen mesothelin on tumor cells." (PMID 36046389, 2020). "This study confirms the potential of Anetumab ravtansine as an anti-tumor agent, however, the results suggest that aiming on a convincing clinical outcome a further dose increase and a restriction to patients displaying a strong intratumoral Mesothelin expression might be necessary." (PMID 32815024, 2020). "This adverse drug effect was attributed to on-target, off-tumor toxicity, resulting from the SS1P targeting of MSLN expressed on the pleural surface." (PMID 32605175, 2020). "The efficacy of the mesothelin-targeting ADC, DMOT4039A, an anti-mesothelin antibody (AMA, MMOT0530A) conjugated to MMAE, was evaluated in a range of tumor models with different levels of MSLN expression." (PMID 33081383, 2020). "PDAC exhibits several tumor-specific antigens, such as carcinoembryonic antigen (CEA), mesothelin (MSLN), and mucin 1 (MUC1), which are promising determinants for CAR T cell therapy." (PMID 31395068, 2019). "A fully human MSLN-targeting CAR (P4) was constructed and shown to be enhanced in terms of cytokine secretion and cytotoxicity in vitro and anti-tumor activity in vivo." (PMID 31463062, 2019). "For example, a PD-1/CD28 switch receptor was engineered into mesothelin-BBζ or PSCA-BBζ CAR T cells, and both switch-receptor CARs performed significantly better than wild type CARs at eradicating tumor in xenograft NSG mouse models." (PMID 30804938, 2019). "A soluble form of Mesothelin, named Soluble Mesothelin-related peptide (SMRP), is shed by the tumor cells into the circulation." (PMID 31475103, 2019). "MSLN has been shown to bind with established cell surface tumor marker MUC16, also known as CA125, leading to increased tumor cell proliferation and metastasis." (PMID 29738555, 2018). "The synergistical phosphorylation of the CD3ζ and 4/1BB signal domains in the presence of cognate tumor cells expressing CEA and MSLN ultimately rendered T cells with complete activation and significant cytotoxicity." (PMID 30103775, 2018). "Anti-tumor cellular immune responses may be directed against: (i) non-mutant but overexpressed targets i.e. mesothelin, NY-ESO-1, survivin, (ii) private mutated proteins (neoantigens) as well as (iii) mutant targets that are shared among different individuals (shared neoantigen), such as KRAS." (PMID 30283732, 2018). "In this dCAR, a tandem construct containing two physically separate structures, CEA-CD3ζ and MSLN-4/1BB signaling domains were effectively controlled with tumor antigens CEA and MSLN, respectively." (PMID 30103775, 2018). "The ADC anetumab ravtansine takes advantage of the tumor-specific expression of its target antigen mesothelin, thereby delivering the highly cytotoxic microtubule-targeting toxophore DM4 payload to tumor cells." (PMID 30344925, 2018). "It has been reported that a sublethal dose of radiation can induce the expression of TAAs, such as mesothelin and CEA, on tumor cells." (PMID 30416506, 2018). "Soluble mesothelin is found in the blood and pleural fluid of patients with MPM and levels correlate with tumour stage and bulk." (PMID 29454314, 2018).
tumor (continued). "In a flow cytometry experiment, data showed that dCAR-T cells had a high proliferation activity in the presence of cognate tumor cells expressing CEA and MSLN, which was similar to that of conventional CAR-T cells (CEA-CAR T or MSLN-CAR T)." (PMID 30103775, 2018). "The dCAR-engineered T cell cytotoxicity was effectively controlled with cognate tumor cells (AsPC-1) expressing CEA and MSLN, thereby mitigating “on-target, off-tumor” toxicity and improving the safety of T cell therapy." (PMID 30103775, 2018). "Based on our in vivo results, 28 days after T cell infusion, mice that received dCAR-T cells showed a marked reduction in tumor burden and even complete tumor remission, which was similar to that of the conventional CAR (CEA-CAR or MSLN-CAR) T cell treatment." (PMID 30103775, 2018). "A tumor vaccine CRS-207 utilizing a live attenuated strain of bacterium Listeria monocytogenes (Lm) expressing human MSLN has shown good tolerance and MSLN-specific T-cell response in a phase I study of safety clinical trial." (PMID 30134520, 2018). "Our results demonstrate the essential role of MSLN in promoting EMT and stemness, as well as tumor formation and metastasis." (PMID 28288645, 2017). "We also performed a flow cytometric assay to confirm surface expression of mesothelin on GBM tumor cells (freshly isolated viable tumor cellscultured in vitro) from five patients, in addition to known GBM tumor cell lines as controls i.e. SNB19 and DBTRG05." (PMID 29113296, 2017). "In preclinical studies with MSLN-expressing tumor bearing mice, 89Zr-anti-MSLN antibody MMOT0530A showed progressive and antigen-specific tumor uptake with micro-PET." (PMID 27252651, 2016). "Known epithelial HGSOC markers such as MSLN, PAX8 and KRT7 were higher in the FTEC isolates, HGSOC tumours and group I cell lines compared with groups II and III cell lines (including IOSEs)." (PMID 27561551, 2016). "In our mouse model, the immune system is intact, and since both B and T lymphocyte responses to mesothelin have been shown to have some protective efficacy, these data suggest there may be some immune interaction in vivo that contributes to the control of tumor growth." (PMID 26931187, 2016). "TCGA-A tumours showed higher expression of most group I/FTEC epithelial proteins such as KRT7, MSLN, CDH6, ASS1 and EPCAM, while TCGA-B tumours had higher expression of the group III/IOSE mesenchymal proteins ITGA5, HMOX1, SMTN and GJA1 (refs 7, 34)." (PMID 27561551, 2016). "Three stably transfected mesothelin over-expressing clones (CMV promoter) were compared to vector and wild type Panc02 injected s.c. for tumor growth kinetics." (PMID 26931187, 2016). "The day 7 flow cytometry numbers of tumor antigen-specific CD8+ T-cells for the SV40-TAg and Mesothelin tetramers in the omentum are illustrated for mice treated with IP M002 and PBS." (PMID 27784340, 2016). "Immunohistochemistry showed that mesothelin was expressed by the HPAC and CAPAN-2 tumors and fluorescence microscopy revealed that AMA-800CW was present in tumor cell cytoplasm." (PMID 26536664, 2015). "When mice with tumors derived from transplanted 634NOD cells were treated with gemcitabine, tumor weight and the level of N-ERC/mesothelin in the serum were decreased compared with control." (PMID 25347530, 2014). "The mean percentage of positive carcinoma cells in tumour tissue was 74% for KOC, 75% for S100P, 73% for mesothelin and 75% for MUC1." (PMID 25071419, 2014). "The mean percentage positivity for biomarkers in tumour vs. normal tissue was as follows: for KOC 74% vs. 0.4%; for S100P 75% vs. 0.3%; for mesothelin 75% vs. 4%; and for MUC1 75% vs. 18% (p < 0.0001 for all tumour vs. normal comparisons)." (PMID 25071419, 2014). "This efficient uptake and maturation allows DC to cross-present tumor antigen, and, thus, to cross-prime CD8+ T cells specific for mesothelin, a tumor antigen expressed by mesothelioma tumor cells." (PMID 24832799, 2013).